TSPO (translocator protein)
Diseases named in the same sentence as TSPO in open-access papers (continued):
Sharing a sentence is not in itself a finding about the gene and the disease.
Sandhoff disease (1 paper, 2020). A lysosomal disorder from the GM2 gangliosidosis family, caused by biallelic pathogenic variants in the HEXB gene, characterized by GM2 ganglioside accumulation in the nervous system and progressive central nervous system degeneration. "We used this animal model because we have previously characterized the TSPO response in microglia and astrocytes that occurs as a result of progressive neurodegeneration in this murine model of Sandhoff disease." (PMID 32743737, 2020). "Furthermore, the TSPO-gp91phox colocalization in the thalamus of Sandhoff disease mice increases as a function of age and progression of neurodegeneration in this preclinical animal model of neurodegeneration." (PMID 32743737, 2020).
seminoma (1 paper, 2016). A radiosensitive malignant germ cell tumor found in the testis (especially undescended), and extragonadal sites (anterior mediastinum and pineal gland). "TSPO protein was expressed in the cytoplasmic compartment of seminoma cells, identified by their nuclear expression of the transcription factors OCT4 and AP2G." (PMID 27608010, 2016). "Taken together, these data showed that TSPO is expressed in seminoma cells, although at lower level than in the presumptive Leydig cells found within some tumors." (PMID 27608010, 2016). "In this case, TSPO appeared as a diffuse and weak signal spread around the nuclei, rather than as the well-defined cytoplasmic ring found in more rounded seminoma cells." (PMID 27608010, 2016). "The comparative study of several normal and seminoma samples revealed a significant upregulation in TSPO mRNA levels in seminomas." (PMID 27608010, 2016). "Immunofluorescent analysis of TSPO and two pluripotency transcription factors OCT3/4 and AP2γ used as seminoma markers confirmed TSPO protein localization in seminoma cells." (PMID 27608010, 2016). "Thus, TSPO appears to be tightly regulated during germ cell differentiation, and to be deregulated in seminomas, suggesting a role in germ cell development and pathology." (PMID 27608010, 2016). "Moreover, our expression studies in human normal testes confirmed that TSPO is expressed in subsets of adult germ cells, suggesting a function in acrosome formation, while the analysis of tumor samples revealed its mRNA up-regulation and protein localization in seminoma cells." (PMID 27608010, 2016). "A comparison of TSPO transcript levels between normal testes and seminoma biopsies showed that seminomas significantly expressed higher levels of TSPO mRNA than normal testicular tissues." (PMID 27608010, 2016). "TSPO protein expression was assessed in paraffin sections from several seminoma cases, in parallel with pluripotency genes OCT3/4 (OCT4; POU5F1) and AP2γ (TFAP2C), considered as seminoma markers." (PMID 27608010, 2016). "By contrast, seminomas, the most common type of TGCT, presented high levels of TSPO mRNA." (PMID 27608010, 2016). "Because of TSPO expression in gonocytes, and the suspected link between impaired gonocytes development and TGCT formation, we next examined whether TSPO might also be expressed in seminoma, the most common type of TGCTs." (PMID 27608010, 2016).
synucleinopathies (1 paper, 2021). "Four challengers ([18F]FEPPA, [11C]PBR28, [11C]DPA-713 and [18F]DPA-714) were used to image TSPO in synucleinopathies, and all 7 studies involved PD patients." (PMID 34387719, 2021).
T-cell leukemia (1 paper, 2023). A malignant disease of the T-lymphocytes in the bone marrow, thymus, and/or blood. "Our finding of an epigenetic regulation of TSPO is in line with results reported in a Jurkat human T cell leukemia cell line where demethylation with 5-aza-2′-deoxycytidine caused a dose-dependent increase in TSPO mRNA." (PMID 37697350, 2023).
testicular cancer (1 paper, 2016). A primary or metastatic malignant neoplasm that affects the testis. "Further studies are needed to determine the exact role of TSPO in normal spermatogenic cell development, from gonocyte to more mature germ cells, and in testicular cancer." (PMID 27608010, 2016).
thyroid carcinoma (1 paper, 2016). "The experiments by Klubo-Gwiezdzinska and colleagues in thyroid carcinoma cell lines knocked down for TSPO showed sixfold increase of TSPO transcript following exposure to valproic acid." (PMID 27077069, 2016).
trisomy 21 (1 paper, 2023). A chromosomal disorder consisting of the presence of an extra chromosome 21. "It binds the translocator protein (TSPO) on the outer mitochondrial membrane and ubiquitination-dependently induced degradation of fragmented mitochondria in fibroblasts derived from a trisomy 21 patient." (PMID 36677746, 2023).
tuberculosis (1 paper, 2018). A chronic, recurrent infection caused by the bacterium Mycobacterium tuberculosis. "[125 I]IodoDPA-713, a radio ligand of TSPO, has been previously used to detect the expression of TSPO in an in vivo mouse model of tuberculosis and [125 I]IodoDPA-713 SPECT activity correlated with lung inflammation after tuberculosis." (PMID 29520214, 2018).
tumor (99 papers, 2001 to 2026). "We also examined the association of TSPO expression with tumor cell stemness and its mutational status across various cancers." (PMID 40936684, 2025). "TSPO expression is closely linked to tumor grades and stages in CRC, suggesting its potential as a diagnostic and prognostic biomarker." (PMID 40550494, 2025). "The findings of this study showed that TSPO is expressed at low levels in tumor tissues, and TSPO deficiency leads to a reduction in lipid accumulation by upregulating GPX4, thereby inhibiting ferroptotic cell death." (PMID 40842566, 2025). "In contrast, at day 14, [18F]GE-180 PET and ARG were already dominated by tumor-associated uptake, and the results in sham mice overall indicated that the inoculation process had less impact on TSPO radioligand uptake at later time points." (PMID 38255293, 2024). "TSPO plays a role in steroid synthesis, regulation of mitochondrial respiration and oxidative stress and its expression has been linked to increased tumor cell proliferation, invasion and overall resistance to apoptosis." (PMID 37158962, 2023). "As a result, elevated TSPO expression was associated with poor tumor differentiation (p = 0.015) and advanced TNM stage (p = 0.027)." (PMID 36994647, 2023). "Surprisingly, in contrast to most previous research, we found that lower TSPO expression associated with higher tumor grade, staging, and worse survival rates." (PMID 38162485, 2023). "It would be highly valuable to monitor changes in TSPO expression during disease progression and its association with individual survival to better understand tumor- as well as treatment- or patient-specific influences." (PMID 36329288, 2023). "A significant (p < 0.001) association was found between higher tumor TSPO expression and lower tumor grade." (PMID 38162485, 2023). "Although the uptake was not only caused by TSPO expressing TAMs, as this recent research showed specific uptake in TSPO-expressing tumor cells as well." (PMID 35788730, 2022). "TSPO was widely expressed by numerous tumor-associated HLA-DR+ (human leukocyte antigen D-associated) and Iba-1+ (microglia/macrophages) myeloid cells in a high-grade glioma patient and to a lesser extent in a low-grade glioma patient." (PMID 35804911, 2022). "TSPO protein and mRNA expression, as well as tumour-associated macrophages (TAMs), were also assessed." (PMID 33340054, 2021). "The association between TSPO and cancer was previously demonstrated and showed elevated TSPO expression levels in case of myeloid and tumor cells, as compared to moderate expression levels in healthy brains." (PMID 34063262, 2021). "While LAT1 was largely restricted to tumor cells, we found that TSPO was also expressed by microglia, tumor-associated macrophages, endothelial cells, and pericytes." (PMID 31963507, 2020). "In our study, the highest TSPO levels were seen in the parenchymal cells in the tumor regions, indicating an upregulation of TSPO in the tumor neo-vasculature and tumor-associated myeloid cells." (PMID 31963507, 2020). "To more precisely evaluate the loss of nuclear and cytoplasmic TSPO expression in tumor cells and confirm the immunofluorescence findings, we dissected mapped tumor and normal adrenal tissue from FFPE unstained slides and performed immunoblots." (PMID 29318061, 2017). "We observed a significant loss of TSPO immunofluorescence expression in the adrenal oncocytic tumor cells when compared to adjacent normal adrenal tissue." (PMID 29318061, 2017). "Immunostains on tissue demonstrated that TSPO was mostly restricted to tumour cells with a contribution of glioma-associated microglial/macrophages (GAMs), but not reactive astrocytes around the lesion." (PMID 27077069, 2016).
tumor (continued). "The purpose of this new analysis, therefore, was to study changes in the normal-appearing brains for this cohort of patients imaged using dynamic [11C](R)PK11195 PET and interrogate the association between tumor growth and expression of TSPO within normal-appearing brain regions." (PMID 38962752, 2024). "Moreover, TSPO expression was not significantly different between primary tumors originating from distinct anatomical sites, but a trend towards a positive association between higher tumor TSPO expression and patient age was seen." (PMID 38162485, 2023). "Patients with high SUVmax had significantly larger contrast-enhancing tumor volumes, and it is tempting to speculate about a causal relationship between these parameters (e.g., high TSPO expression leads to fast tumor growth)." (PMID 36329288, 2023). "However, in p16-positive tumors, lower tumor TSPO expression associated with worse OS (p < 0.001) and DSS (p = 0.004)." (PMID 38162485, 2023). "Previous studies have implicated TSPO may play a role in tumor, thus we chose TSPO for further investigation." (PMID 36994647, 2023). "The coincidence of genuine tumor cell–associated TSPO expression and neuroinflammation in glioblastoma underscores that TSPO PET could be a valuable imaging modality in glioblastoma patients as well." (PMID 37536737, 2023). "Since Nrf2 is an important and ubiquitously expressed transcription factor in tumor cells, we hypothesized that PD‐L1 downregulation caused by TSPO knockdown is regulated at the transcriptional level through Nrf2." (PMID 36994647, 2023). "Within the heterogeneous glioma tissue, neoplastic tumor cells, glioma-associated microglia/macrophages, astrocytes, monocytic-MDSCs, endothelial cells and pericytes express the 18 kDa translocator protein (TSPO)." (PMID 35804911, 2022). "TSPO is implicated in multiple cellular processes, including the translocation of cholesterol and steroidogenesis, porphyrin transport, cellular responses to stress, inflammation, and tumor progression." (PMID 35444539, 2022). "The utilization of CD206 and TSPO as targets for tumor-associated macrophages could address FDG’s limitations in regard to specificity." (PMID 33923410, 2021). "Indeed, we found, by immunofluorescent staining, that TSPO was expressed in tumor-associated myeloid cells marked by Iba1 expression." (PMID 31963507, 2020). "In the patient-derived xenografts (PDX) and murine GBMs of different genetic subtypes, a high expression of TSPO in Iba1-positive tumor-associated cells could be found (arrows)." (PMID 31963507, 2020). "Modulation of TSPO activity through specific TSPO ligands could pave the way for attenuating this flexibility and making the tumor more susceptible to tumor-specific treatments." (PMID 33066460, 2020). "Multiple images captured from tumor cells and normal adrenal gland showed strong immunofluorescence positivity in the normal adjacent adrenal gland and significant loss of TSPO expression in the tumor cells." (PMID 29318061, 2017). "Interestingly, low tumor TSPO expression associated with worse OS (p = 0.001) and DSS (p < 0.001)." (PMID 38162485, 2023). "In addition, cleavage of caspase-9/-3 and PARP1 was increased in PI3/SLPI-deficient cells upon TRAIL treatment, substantiating the tumor-protective role of these two peptidase inhibitors through regulation of both intrinsic and extrinsic apoptosis pathways downstream of TSPO." (PMID 37158962, 2023). "However, it remains unclear to which extent the TSPO expression reflects tumor tissue or glioma-associated immune cells." (PMID 35804911, 2022). "Interestingly, increased expression of TSPO was reported also in several cancer cell lines as well as in tumor-associated macrophages, suggesting that TSPO could play a role also in tumorigenesis." (PMID 34203263, 2021).
tumor (continued). "The expression of TSPO can be detected in tumor cells of different experimental mouse models, as well as in tumor parenchymal cells, such as endothelial cells and pericytes of the tumor neo-vasculature, and tumor-associated myeloid cells, independent of the GBM genetic subtype." (PMID 31963507, 2020). "We prioritized FKBP5 (HP pharmacodynamics) and CLDN4 (tumor baseline) as the main candidates; TSPO and SGK1 are reported as exploratory." (PMID 41614938, 2026). "Tumour specimens from HerGa treatments also exhibited downregulation of HER3 and the mitochondrial metabolic marker, TSPO, in contrast to S2Ga treatment, agreeing with the mitochondrial targeting of corroles once inside the tumour cell." (PMID 39984637, 2025). "Kaplan–Meier survival analysis based on the TCGA database further indicated that high expression of TSPO was significantly associated with longer overall survival (OS) (P = 7.0e-4, HR = 0.41, 95% CI = 0.24–0.70), suggesting that TSPO may possess tumor-suppressive functions." (PMID 40936684, 2025). "Recent studies have demonstrated that transcription of TSPO is down-regulated in M1 macrophages but remains unaltered in M2 type macrophages, rendering TSPO a potential target for in vivo visualization of M2-like macrophages in the tumor stroma." (PMID 40725764, 2025). "The results showed that TSPO protein expression in MPNST tissues was lower than that in the adjacent non-tumor tissues." (PMID 40842566, 2025). "Patients under 50 years exhibited mean TSPO expression levels of 9.00 in tumor tissues and 8.84 in non‐tumor tissues." (PMID 40550494, 2025). "Further in-depth mechanistic investigations—including in vivo studies—are also needed to elucidate the precise molecular role of TSPO in tumor progression and stem cell regulation in ESCA." (PMID 40936684, 2025). "RT‐PCR to analyze TSPO gene expression in both tumor and marginal tissue samples is a robust method, ensuring reliable and precise measurement of gene expression levels." (PMID 40550494, 2025). "A significant increase in TSPO gene expression was observed in CRC tumor tissues compared to normal samples (p < 0.001)." (PMID 40550494, 2025). "The study findings revealed a highly significant difference in TSPO gene expression between CRC tumor samples and normal tissue samples." (PMID 40550494, 2025). "The observed correlation between TSPO expression and tumor grade aligns with previous similar studies." (PMID 40550494, 2025). "Grade IV tumors also had elevated TSPO expression, with a mean of 18.39 in tumor tissues and 13.40 in non‐tumor tissues." (PMID 40550494, 2025). "The p‐values for these comparisons were significant (p = 0.001 for tumor tissues and p = 0.010 for non‐tumor tissues), indicating significant variations in TSPO expression across different cancer stages." (PMID 40550494, 2025). "Experimentally, we performed clonogenic assays and CCK-8 assays to verify the enhanced proliferative capacity of tumor cells following TSPO overexpression." (PMID 40936684, 2025). "The p‐values indicated a significant increase in TSPO expression with higher tumor grades (p < 0.001 for tumor tissues and p = 0.123 for non‐tumor tissues)." (PMID 40550494, 2025). "Conversely, in tumor tissues with low TSPO expression, AKR1C1 and FTH1 are similarly found to have low expression." (PMID 40842566, 2025). "TSPO's elevated expression in CRC and its association with tumor aggressiveness make it a valuable biomarker for diagnostic and prognostic purposes." (PMID 40550494, 2025). "Ang-2 drives pathological angiogenesis, vascular leak, and recruitment of immunosuppressive cells such as TAMs 40, 43, whereas high TSPO expression amplifies anti-apoptotic signaling that protects tumor cells from therapy-induced death." (PMID 41209565, 2025). "Statistical analysis revealed a highly significant difference in TSPO gene expression in CRC tumor samples compared to normal tissue samples (p < 0.001)." (PMID 40550494, 2025).